CCNT1 (cyclin T1)
Diseases named in the same sentence as CCNT1 in open-access papers:
CCNT1 is named in the same sentence as 42 diseases in open-access papers, as found by Europe PMC text mining. Sharing a sentence is not in itself a finding about the gene and the disease. The quoted sentences say what the papers report.
HIV-1 infection (19 papers, 2006 to 2024). The type species of lentivirus and the etiologic agent of acquired immunodeficiency syndrome (AIDS). "Given the canonical role of CCNT1 residue C261 in HIV-1 infection, we hypothesized that CCNT1.C261Y cells would be susceptible to HIV-1 infection but would yield a forced latency phenotype downstream of proviral integration due to Tat inactivation." (PMID 37676006, 2023). "In search for additional factors limiting the productive HIV-1 infection in U937 Minus cells, we evaluated the expression of the Cyclin T1 component of P-TEFb complex by Western blot." (PMID 39205150, 2024). "As expected, the Cyclin T1 specific gene-list was over-represented for genes involved in HIV-1 infection." (PMID 21791050, 2011). "We observed that HIV-1 infection of macrophages modestly induces both miR-198 and Cyclin T1 mRNA expression levels." (PMID 19148268, 2009). "After it is shut-off in late-differentiated macrophages, Cyclin T1 can be re-induced by activation with agents such as LPS or by HIV-1 infection, indicating that the induction of Cyclin T1 is a component of an innate immune response in mature macrophages." (PMID 18773076, 2008). "We have shown that the knockdown of cyclin T1 in MM6 cells has a pronounced effect on Tat transactivation during HIV-1 infection." (PMID 16764723, 2006). "For instance, knockout of previously known HIV-1 interactors Cyclin T1 (CCNT1), Peptidylprolyl isomerase A (CYPA) and Lens epithelium–derived growth factor (LEDGF) reduced susceptibility to HIV-1 infection of primary human CD4+ T cells to approximately 20 percent of wild-type T cells." (PMID 35892930, 2022). "This raises questions about using cyclin T1 as a therapeutic target for HIV-1 infection." (PMID 16764723, 2006). "A number of factors in host cells have been implicated to be involved in the early and late phases of HIV-1 infection; e.g., CD4 as the major receptor for HIV-1 entry, chemokine receptors as coreceptors and cyclin T1 (CycT1) for the efficient viral transcription through binding to HIV-1 Tat." (PMID 24381568, 2013). "However, CCNT1 but not CCNT2 expression can be up-regulated in late differentiated macrophage by either HIV-1 infection or activation with pathogen-associated molecular patterns (PAMPs)." (PMID 23110726, 2012). "Additionally, Cyclin T1 protein expression is shut-off at late times of macrophage differentiation by proteasome-mediated proteolysis, but it can be re-induced by macrophage activation or HIV-1 infection." (PMID 19148268, 2009). "Furthermore, analysis of the Transgene-Expression-per-Integrant suggests that a cyclin T1-independent transcriptional defect may impose an additional peri-integrational limitation for a productive HIV-1 infection at least in some mouse T-cell lines." (PMID 18611257, 2008). "Taken together, these findings underscore the role of Cyclin T1 as a key regulator of Tat-mediated HIV-1 transcription and elucidate another mechanism utilized by U937 Minus cells to maintain their poorly permissive phenotype to HIV-1 infection." (PMID 39205150, 2024). "Immunofluorescence confirmed that a significant fraction of the CCNT1 subunit of P-TEFb was localized to the cytoplasm, consistent with a previous observation that CCNT1 and CDK9 are detected in the cytoplasm in unstimulated resting memory CD4+ T cells, the target immune cells of HIV-1 infection." (PMID 29845934, 2018).
breast carcinoma (7 papers, 2015 to 2024). "Among the hubs of the 6 modules, 5 of them (PTPN22, BRIP1, CEACAM6, LTF, and CCNT1) have been previously found to be associated with breast cancer, and the other one, MXRA5, has been reported to be related to non-small cell lung cancer." (PMID 30240439, 2018). "Six breast cancer differentially localized proteins were got: CCNT1, NSUN5, PRPF4, RECQL4, UTP6, ZNF500." (PMID 39095659, 2024). "CCNT1 was enriched in the 7SK snRNA binding process, 7SK snRNA involved in the regulation of positive transcription elongation factor b on the epithelial–mesenchymal transition, which is important for breast cancer progression." (PMID 39095659, 2024). "The ultimate molecular function of CCNT1 and its interactions with CLOCK and the other predicted genes remains elusive, and any potential role in breast cancer is largely unremarked, as only 3 papers within PubMed mention CCNT1 and breast cancer, and in fact only 39 papers mention CCNT1 and cancer." (PMID 34056582, 2021). "Similarly, the high expression of cyclin T1 correlated with an improved disease-free survival of patients with stomach adenocarcinoma and high CDK9 expression was associated with prolonged survival in breast cancer." (PMID 36979907, 2023). "Based on the results of survival analysis (p < 0.05), it was found that the results of UTP6, NSUN5 and RECQL4 proteins were more relevant to the prognosis of breast cancer, while the results of CCNT1 and PRPF4 were not." (PMID 39095659, 2024).
leukemia (4 papers, 2005 to 2022). A malignant (clonal) hematologic disorder, involving hematopoietic stem cells and characterized by the presence of primitive or atypical myeloid or lymphoid cells in the bone marrow and the blood. "Most frequent MLL1-fusion partners AF4/AFF4, AF9/ENL and ELL, together with CDK9/cyclin-T1, constitute super elongation complexes (SEC), which promote aberrant gene transcription, oncogenesis and maintenance of MLL1-rearranged (MLL1-r) leukemia." (PMID 35395864, 2022). "Therefore, targeting the PPIs between cyclin-T1 and AFF4/AF4 represents a potential therapeutic approach to the treatment of MLL1-r leukemia and HIV infection." (PMID 33823889, 2021). "To determine whether the induction of cyclin T1 protein can be recapitulated in a transformed cell line that is more amenable to functional studies, we examined the Mono-Mac-6 (MM6) cell line that was derived from a human leukemia patient." (PMID 16764723, 2006).
virus infection (3 papers, 2006 to 2021). "The increased association of Cyclin T1 with CDK9 leads to elevated Cyclin T1/P-TEFb kinase activity, and this appears to be utilized by the HIV-1 Tat protein to stimulate viral LTR-directed transcription as suggested by our results with Tat+ reporter virus infection." (PMID 17014716, 2006).
cardiac hypertrophy (2 papers, 2020 to 2022). "In addition, cardiomyocyte-specific transgenic overexpression of Cyclin-T1, a key component of the CDK9-activating complex, was sufficient to drive pathological cardiac hypertrophy in mice in vivo." (PMID 35896549, 2022).
follicular lymphoma (2 papers, 2013 to 2015). Follicular lymphoma is a form of non-Hodgkin lymphoma characterized by a proliferation of B cells whose nodular structure of follicular architecture is preserved. "Overexpression of CDK9 and cyclin T1 has been reported in B and T cell precursor-derived lymphomas, anaplastic large T cell lymphoma, and follicular lymphomas, while strong nuclear staining of these proteins has been described in classical Hodgkin’s lymphoma." (PMID 25625291, 2015). "Abnormal mRNA levels of CDK9 and cyclin T1 have been found in Burkitt’s lymphoma, diffuse large B cell lymphoma with germinal center phenotype, classical Hodgkin’s lymphoma-derived cell lines, and follicular lymphoma." (PMID 25625291, 2015). "In addition, abnormal mRNA levels of CDK9 and cyclin T1 were found in Burkitt's lymphoma, diffuse large B cell lymphoma with germinal center phenotype, classical Hodgkin's lymphoma-derived cell lines, and follicular lymphoma." (PMID 23840966, 2013).
heart failure (2 papers, 2015 to 2022). Inability of the heart to pump blood at an adequate rate to meet tissue metabolic requirements. "Continuous activation of the Cdk9/Cyclin T1 complex induces not only cardiomyocyte hypertrophy but also cardiac apoptosis by disrupting mitochondrial function, suggesting that the Cdk9/Cyclin T1 complex is a novel target for heart-failure therapy." (PMID 35745840, 2022).
lymphoma (2 papers, 2020 to 2023). A malignant (clonal) proliferation of B- lymphocytes or T- lymphocytes which involves the lymph nodes, bone marrow and/or extranodal sites. "An imbalance of expression levels between CDK9 and CCNT1 has been found in several lymphoma types, suggesting a common mechanism of deregulation of transcription in the neoplastic transformation of these cells." (PMID 37756103, 2023). "There were also significant haplotypes that had SNPs spanning CCNT1 (5 SNP haplotype) and PFKM (4 SNP haplotype), both of which were more common in lymphoma cases (13–19%) compared to controls (13%)." (PMID 37756103, 2023).
Arthritis (1 paper, 2016). Inflammation of a joint. "CDK9 (Cyclin-dependent kinase 9)/Cyclin T1/RNA polymerase II pathway has been demonstrated to promote the development of several inflammatory diseases, such as arthritis or atherosclerosis, however, its roles in allotransplantation rejection have not been addressed." (PMID 27102157, 2016).
chronic lymphocytic leukemia (1 paper, 2012). "Recently, the CDK9 inhibitor flavopiridol was shown to induce apoptosis in primary chronic lymphocytic leukemia by targeting CDK9, cyclin T1, AFF3/4 and MLLT1." (PMID 23140174, 2012).
gastric cancer (1 paper, 2023). A primary or metastatic malignant neoplasm involving the stomach. "PGC expression suppressed the proliferation and invasion of gastric cancer cells possibly by interacting with CCNT1, CNDP2 and CTSB." (PMID 37291517, 2023). "PGC expression suppressed the proliferation, anti-apoptosis, migration and invasion of gastric cancer cells possibly by interaction with CCNT1, CNDP2 and CTSB." (PMID 37291517, 2023).
glioma (1 paper, 2020). A benign or malignant brain and spinal cord tumor that arises from glial cells (astrocytes, oligodendrocytes, ependymal cells). "The top five scored genes (TAF1, TAFL1, CBL, CCNT1, and RMNT) were further analyzed in the glioma tissues samples in the CGGA database." (PMID 32322592, 2020).
latent infection (1 paper, 2014). "Positively Tat-regulating factors such as CCNT1, protein phospatase 1(PP1), and p300/CBP did not have lower expression levels in latent cells compared with normal cells, suggesting that the basal expression of these factors may not be associated with latent infection." (PMID 25116364, 2014).
lentivirus infection (1 paper, 2006). Virus diseases caused by the Lentivirus genus. "We do note, however, that in non-PMA-treated cells the cyclin T1 knock-down induced a small number of PMA-upregulated genes >2-fold, suggesting a very low level of activation occurred following the shRNA-CycT1 lentivirus infection." (PMID 16764723, 2006).
mantle cell lymphoma (1 paper, 2024). Mantle cell lymphoma is a rare form of malignant non-Hodgkin lymphoma affecting B lymphocytes in the lymph nodes in a region called the ``mantle zone''. "In particular, flavopiridol was a nonselective CDK9 inhibitor (CDK9/cyclin T1 Ki = 3 nM) which showed in vivo activity in hematologic malignancies (e.g., mantle cell lymphoma, CLL) but was halted due to high toxicity." (PMID 38172923, 2024).
mastitis (1 paper, 2024). Inflammation of breast tissue during lactation or postpartum due to an obstructed duct or infection. "These genes included CCNT1, previously associated with milk and cheese-making traits; LALBA, associated with milk production traits; MRPL42, a candidate gene for mastitis resistance; and the gene suppressor of cytokine signaling 2 (SOCS2) associated with mastitis susceptibility." (PMID 39080565, 2024).
myoclonus dystonia (1 paper, 2024). "A novel homozygous variant (NM_001240;c.1972C>G;p.Q658E) of another compelling gene, CCNT1, was identified in one patient (DYS-80; II.2) presenting with childhood-onset myoclonus dystonia." (PMID 38458754, 2024).
pancreatic cancer (1 paper, 2017). "Overall, new chemical entity based on symmetrical bis-pyrrolo[2,3-d]pyrimidines connected through di(ethylene-1,2,3-triazolyl)phenyl spacer was identified as a novel CDK9/cyclin T1 inhibitor for potential treatment of pancreatic cancer." (PMID 29104242, 2017).
prostate carcinoma (1 paper, 2015). A carcinoma that arises from epithelial cells of the prostate gland. "These represented cell cycle/mitosis; among others CCNE1, CCNE2, CCNG2, CCNL1, CCNT1, CDK12 and CDKN3, prostate cancer; including the androgen receptor (AR), metabolism as well as targets of the transcription factors E2F, AP2, SP1, ETF and Pax3." (PMID 26698305, 2015).
infection (16 papers, 2006 to 2024). The state of being infected such as from the introduction of a foreign agent such as serum, vaccine, antigenic substance or organism. "After infection with a dual-reporter virus, the infected cells were knocked out by electroporation with Cas9 and gRNA for CCNT1 or control AAVS1." (PMID 37766271, 2023). "We stimulated CD4+ T cells from three different donors with equimolar concentrations of IL-2 and IL-15 and analyzed the expression of CDK9 and cyclin T1 after 8 to 9 days of stimulation, a time when latent and productive infection with HIV-GKO was measured." (PMID 35499323, 2022). "At 24 h post infection, we observed equivalent numbers of mCherry-positive (~15%) cells for both the CCNT1.C261Y and parental control cells, confirming that HIV-1 entry is not altered in CCNT1.C261Y cell lines and that the antiviral effects occur post-integration." (PMID 37676006, 2023). "Finally, we determined CDK9 and cyclin T1 expression, as well as NF-κB localization, at the time when we analyzed the outcome of infection; we cannot exclude that earlier time points might be relevant as well." (PMID 35499323, 2022). "This may reflect differences in ICP22 action when it is ectopically expressed in cells on its own in our experiments and ICP22 action in the context of infection, differences in the effect on host cell and viral genes or that ICP22 has different effects on CDK9 and Cyclin T1 association." (PMID 25233083, 2014). "Knock-out of each P-TEFb component (CCNT1, CDK9) significantly decreased infection." (PMID 39259751, 2024). "For example, non-env-interacting protein cyclin T1 (CCNT1) interacts with HIV-1 during infection as it is targeted by gag and tat proteins." (PMID 35134057, 2022). "This indicated that while expression of the human CD4, CCR5 and cyclin T1 transgenes enabled the hCD4/R5/cT1 mouse CD4+ T cells and myeloid-lineage cells to be infected with HIV-1, hCD4/R5/cT1 mouse myeloid-lineage cells supported infection more robustly than the CD4+ T cells." (PMID 23691059, 2013). "At 48 hours post-infection with reporter viruses, siRNAs against CDK11, negative control siRNAs, or a positive control of siRNAs against Cyclin T1 were transfected into cells." (PMID 18773076, 2008).
tumor (14 papers, 2012 to 2025). "The iridium­(III) core imparts near-infrared luminescence,enabling real-time imaging of CCNT1 in TNBC cells and tumor spheroidswhile distinguishing cancerous cells (with a high level of CCNT1 expression)from normal cells." (PMID 41152016, 2025). "In PCa, PSA eRNA with a TAR‐L motif recruits CYCLIN T1 and activates the CYCLIN T1/P‐TEFb/Pol II Ser2 axis, facilitating castration‐resistant tumor growth." (PMID 40761481, 2025). "RECQL4, UTP6, CCNT1, and NSUN5 were enriched in the regulation process of cyclin dependent protein kinase activity, Cyclin D1 is one of the effectors of tumor gene Neu and Ras causing malignant transformation of cells in breast cancer." (PMID 39095659, 2024). "Roniciclib binds to and inhibits the activity of CDK1/Cyclin B, CDK2/Cyclin E, CDK4/Cyclin D1, CDK6/Cyclin D3, and CDK9/Cyclin T1, which are serine/threonine kinases playing key roles in the regulation of tumor cell proliferation and survival." (PMID 32737364, 2020). "Because very few edges are shared between any pair of networks inferred by WGCNA, there is only one hub gene (CCNT1) in the tumor-shared network." (PMID 30240439, 2018). "In addition, cyclin T1 has also been reported to be overexpressed in cancer tissues compared to normal tissues, enhancing transcription elongation, and promoting tumor malignances." (PMID 35088192, 2023). "Designs for future studies might use conditional genetic knockout of the CDK9 or cyclin T1/2 genes in various established cancer models to provide more information about the role of the P-TEFb complex in tumor formation." (PMID 34041038, 2021). "Overexpression of CCNT1 was found as an implication of tumor growth." (PMID 30240439, 2018). "In metastatic TNBC models, complex 8 reduced the coprecipitation between CCNT1 and CDK9 and decreasedmRNA levels of c-MYC and Mcl-1 in tumor tissues, which suggested thatcomplex 8 disrupted the CDK9–CCNT1 PPI in vivo." (PMID 41152016, 2025). "Remarkably, studies conducted on Iron chelators ICL670 and ICL311 reported kinase activity inhibition following the separation of CDK9 from cyclin T1, which, in turn, resulted either in suppression of HIV-1 replication or repression of tumor growth in vitro and in animal models." (PMID 23840966, 2013).
cancer (11 papers, 2018 to 2026). A tumor composed of atypical neoplastic, often pleomorphic cells that invade other tissues. "Quantitative RT–PCR (qRT-PCR) further showed that Bcat1 (related to BCAA metabolism) or Hoxa9, Ccnt1, Pbx1, Rora and Pbx3 (related to transcriptional misregulation in cancer) were significantly reduced in P2x1-null LICs, suggesting that these genes may act as downstream targets of P2X1." (PMID 36418376, 2023). "This compound also inhibits the cell migration in MDA-MB-231 cancer cell lines and was reported as the first non-metal–organic structure that works as a selective CDK9/Cyclin T1 with in vivo anticancer activities." (PMID 39404419, 2024).
cardiovascular diseases (1 paper, 2011). "Cyclin T2 specific genes were over represented only in the aging process while metabolic and cardiovascular diseases were linked to genes that were commonly down-regulated upon Cyclin T2 or Cyclin T1 depletion." (PMID 21791050, 2011).
neurological diseases (1 paper, 2024). "For example, SLP1, sortilin, and EPHA2 are specifically distributed in the nervous system and function in neurological diseases; CCNT1 is related to HIV infections; while TNFRs (TNFR1, TNFR2) are associated with inflammatory regulation, of which TNFR2 usually involves anti-inflammatory responses." (PMID 38689292, 2024).
CCNT1 also shares sentences with these, for which no sentence is quoted: Hodgkins lymphoma (2 papers); acute myeloid leukaemia (1); AIDS (1); atherosclerosis (1); diffuse midline glioma (1); Dystonia (1); fibrosarcoma (1); gastritis (1); hematologic malignancies (1); lung carcinoma (1); melanoma (1); non-small cell lung carcinoma (1); oral cancer (1); osteonecrosis (1); Parkinsonism (1); sarcoma (1); Spastic paraplegia 7 (1); stomach adenocarcinoma (1).